BDNF (brain derived neurotrophic factor)
Diseases named in the same sentence as BDNF in open-access papers (continued):
Sharing a sentence is not in itself a finding about the gene and the disease.
glioma (continued). "We observed that BDNF induced IL-15 production by microglia only upon treatment with IL-4 or co-culture with glioma cells." (PMID 29286001, 2017). "Above: scheme of striatal infusion of vehicle or BDNF with micro-osmotic pumps starting 10 days after glioma cell transplantation and lasting 7 days, in SE mice." (PMID 29286001, 2017). "All together, these data suggest that BDNF induces the release of soluble factors by the glioma, acting on microglia to modulate phagocytosis and chemotaxis." (PMID 25818172, 2015). "Direct infusion of IL-15 or BDNF in the brain of mice transplanted with glioma significantly reduces tumour growth." (PMID 25818172, 2015). "Expression of HERV-W env in human glioma cells results in a two- to fourfold increase in expression of brain-derived neurotrophic factor (BDNF), neurotrophic tyrosine kinase receptor type 2 (NTRK2), and dopamine receptor D3 (DRD3)." (PMID 26793126, 2015). "Interleukin-15 (IL-15) and BDNF are two key mediators of these effects, since they increase in the brain of EE mice, and their in situ administration reduces tumour size in glioma-bearing mice, similarly to EE." (PMID 25818172, 2015). "While IL-15 produced by CD11b+ cells modulates NK cell infiltration and antitumour activity, BDNF reduces M/Mφ infiltration and the invasion of cerebral parenchyma by glioma cells through Trkb.T1, both contributing to limit glioma expansion." (PMID 25818172, 2015). "On EE exposure, a significant increase in BDNF is observed in both the hemispheres of sham-operated (P<0.05, Student’s t-test, n=3) and glioma-bearing mice (P<0.01, Student’s t-test, n=4)." (PMID 25818172, 2015). "Similar results are obtained when BDNF (or vehicle) is delivered 10 days after glioma transplantation into the brain of SE mice with micro-osmotic pumps, for 7 days (100 ng ml−1, 100 μl, 0.5 μl h−1)." (PMID 25818172, 2015). "To further investigate the direct effects of BDNF on glioma, we analysed the expression of TrkB receptors on GL261 cells using RT–PCR and western blot analyses." (PMID 25818172, 2015). "BDNF has direct effects on tumour cells, reducing glioma cell migration in vitro and impairing the expression of the phagocytic marker CD68 on M/Mφ, and their infiltration in the tumour mass." (PMID 25818172, 2015). "Recent studies have highlighted the importance of the glioma–neuron interactions in this process, showing that the glioma cells are synaptically integrated to the normal neuronal circuitry and receive survival signals through neuronal secretion of BDNF and NLGN3." (PMID 40867165, 2025). "Characteristics of studies evaluating the relation between BDNF levels in glioma." (PMID 39789839, 2025). "However, our findings showed significant plasma concentration differences between high‐ and low‐grade gliomas, suggesting BDNF as a potential marker for glioma grading." (PMID 39789839, 2025). "Hence, there is a need to search for new strategies to decrease the BDNF level and formation of migrasome as a target to prevent metastases and discover therapy for various cancers such as glioma." (PMID 38775506, 2024). "In addition, immunoelectron microscopy studies have revealed that the BDNF/TrkB signaling pathway can increase the number of synaptic connections between neurons and glioma cells." (PMID 39469896, 2024). "Further research has demonstrated that genetically or pharmacologically inhibiting TrkB not only negates BDNF's influence on glioma synaptic activity but also significantly enhances the survival rates in xenograft models of pediatric glioblastoma and diffuse pontine glioma." (PMID 39469896, 2024). "These astrocytes are indirectly involved in glioma spreading, including a metabolic way, by synthetizing multiple cytokines: brain-derived neurotrophic factor (BDNF), transforming growth factor α (TGF-α), sphingosine-1-phosphate, glial cell line-derived neurotrophic factor (GDNF)." (PMID 39539752, 2024).
glioma (continued). "Evidence that BDNF exerts anti-tumorigenic activity includes the following: First, infusion of BDNF into a glioma-bearing mouse brain suppressed tumor growth and migration via a truncated TrkB.T1 receptor-dependent mechanism; it also suppressed intra-tumoral macrophage infiltration." (PMID 38928185, 2024). "Furthermore, the presence of BDNF and TrkB has also been noted in human gangliogliomas, underscoring their role in glioma biology." (PMID 39469896, 2024). "Therefore, the aim of this study was to investigate the effects of Anax imperator adipokinetic hormone on brain-derived neurotrophic factor expression and ultrastructure of cells in the C6 glioma cell line." (PMID 38775506, 2024). "BDNF–TrkB signalling also regulates the number of neuron-to-glioma synapses." (PMID 37914930, 2023). "Time-course imaging of individual puncta demonstrated that BDNF exposure elicits an increase in the postsynaptic levels of GluA2 on the glioma cells, on a time-scale consistent with the increased GluA3 and GluA4 trafficking and the change in glutamate-evoked currents." (PMID 37914930, 2023). "We next explored the signalling mechanisms of BDNF in patient-derived paediatric glioma cells." (PMID 37914930, 2023). "Glioma EPSCs increased in amplitude following exposure to BDNF." (PMID 37914930, 2023). "Consistent with the hypothesis that BDNF increases AMPAR trafficking to the glioma cell membrane, BDNF exposure increased glioma cell surface levels of the AMPAR subunits GluA3 and GluA4 compared with vehicle-treated control glioma cells." (PMID 37914930, 2023). "We therefore tested the hypothesis that BDNF–TrkB signalling could induce plasticity of the malignant synapse—that is, it could increase the amplitude of glioma excitatory postsynaptic currents (EPSCs)." (PMID 37914930, 2023). "We hypothesized that BDNF–TrkB signalling may function in glioma to strengthen neuron-to-glioma synapses." (PMID 37914930, 2023). "BDNF action is mediated by tropomyosin receptor kinase B, whose expression in gliomas may promote tumor growth and progression toward malignancy." (PMID 38050515, 2023). "Additionally, glioma cells had increased motility and invasion in the presence of BDNF, as well as decreased rates of apoptosis." (PMID 36968288, 2023). "Differentiated GBM cells can produce 1.97-fold more mature-BDNF compared to lower-grade gliomas." (PMID 37686652, 2023). "To investigate whether BDNF–TrkB signalling regulates the number of neuron-to-glioma synaptic connections, we performed immuno-electron microscopy in the brains of mice bearing wild-type and NTRK2-KO patient-derived glioma xenografts expressing GFP." (PMID 37914930, 2023). "Both NLGN34 and BDNF promote neuron-to-glioma synapse formation." (PMID 37914930, 2023). "However, rs4702‐A was associated with increased expression of FURIN and BDNF in the serum and PBMC of glioma patients after radiotherapy." (PMID 34953024, 2022). "Similarly, one study reported that GAMs, stimulated by the brain-derived neurotrophic factor (BDNF), increased NK cell infiltration and activation, thus contributing to the modulation of glioma expansion." (PMID 35163235, 2022). "Additionally, BDNF regulates trafficking of AMPAR to the postsynaptic membrane in glioma cells and promotes glioma progression through neurotrophic tyrosine kinase receptor 2 (NTRK2) in a neuronal activity-dependent manner." (PMID 36357661, 2022). "BDNF stimulates the production of Interleukin-15 (IL-15) in the brain of glioma-mice, and IL-15, in turn, stimulates natural kill (NK) cells to produce Interferon-gamma (IFN-γ) that affects the phenotype of myeloid cells, promoting the transition to an anti-tumour state." (PMID 34489641, 2021).
glioma (continued). "In conclusion, the present study employed an activity-guided fractionation methodology which led to the identification of benzyl 6-O-β-D-apiofuranosyl-b-D-glucoside (B6AG) as a natural product from sage leaves that upregulates BDNF mRNA expression in C6 glioma cells." (PMID 34299002, 2021). "Recent studies demonstrated that BDNF participates in the carcinogenesis of glioma." (PMID 33817216, 2020). "Additionally, P75NTR is upregulated in GBM and mediates the function of pro-BDNF to inhibit glioma cell growth." (PMID 32046730, 2020). "MiR-103 suppressed glioma cell proliferation and invasion by targeting BDNF." (PMID 33817216, 2020). "Brain-derived neurotrophic factor (BDNF) release also accelerated glioma cell proliferation." (PMID 33187183, 2020). "Moreover, the reduced expression patterns of stemness-associated genes (MYC and SOX2) and the reactivation of neuronal differentiation-associated genes (BDNF, NGF, and NTF3) were clearly observed in the asTUG1/uPIC-treated glioma tissues." (PMID 31019193, 2019). "In glioma patients, the expression of BDNF was significantly higher compared to control." (PMID 30233327, 2018). "Furthermore, many studies reported that the Akt and Src are common downstream signaling kinase of BDNF and play an important role in glioma development." (PMID 30233327, 2018). "The BDNF derived from the brain-stimulated microglial cells to produce IL-15 and consequently increase NK cell infiltration and activation, contributing to limit glioma expansion." (PMID 30123112, 2018). "Indeed, high expressions of both pro-BDNF and p75NTR are observed in high grade gliomas with invasive properties." (PMID 27120782, 2016). "However, BDNF hampers the increase in phagocytic and chemotactic activities induced on the microglia by co-culturing with glioma cells." (PMID 25818172, 2015). "We demonstrate that the reduction in glioma size in EE-housed mice is mediated by an increase in brain IL-15, which favours NK cell accumulation and antitumour function, and BDNF, which suppresses M/Mφ infiltration and activity, and directly affects tumour cell migration." (PMID 25818172, 2015). "Our data point to an unambiguous inhibitory effect on glioma growth by BDNF signalling." (PMID 25818172, 2015). "Thus, attentively modulating the balance between mature BDNF and proBDNF levels could promisingly affect glioma progression as a potential therapeutic target." (PMID 39789839, 2025). "Notably, BDNF also plays a crucial role in neuron-glioma interactions." (PMID 40092993, 2025). "Therefore, the expression of brain-derived neurotrophic factor and migrasome formation may be promising targets for preventing tumor proliferation, invasion, and metastasis in glioma." (PMID 38775506, 2024). "Also the role of BDNF in the regulation of glioma growth remains controversial." (PMID 34690699, 2021). "Transcriptional regulators of HNRNPK such as brain-derived neurotrophic factor (BDNF) were upregulated in gliomas, and we hypothesized that the AGPS-HNRNPK complex could facilitate to regulate tumor-related mRNA by BDNF, which would be explored in further study." (PMID 34621897, 2021). "Therefore, each P1–4 sample was screened for changes in BDNF mRNA expression in C6 glioma cells." (PMID 34299002, 2021). "Therefore, it was speculated that the neuroprotective effects of TEA in C6 glioma cells might be mediated by the BDNF/TrkB-ERK/PI3K-CREB signaling pathway." (PMID 34975553, 2021). "In particular, a recent study has demonstrated that glioma-bearing mice exposed to EE showed a reduced tumor size with respect to a standard environment, together with an increase of interleukin 15 (IL-15) and Brain-derived neurotrophic factor (BDNF) intracerebral levels." (PMID 32764487, 2020).
glioma (continued). "Indeed, it has been shown that neuronal excitation and subsequent release of synaptic adhesion protein Neuroligin-3 (NLGN3), Brain Derived Neurotrophic Factor (BDNF), and neurotransmitter such as dopamine and serotonin are utilized by glioma cells to promote tumor growth." (PMID 31396225, 2019). "We report that EE exposure affects: (i) tumour size, increasing mice survival; (ii) glioma establishment, proliferation and invasion; (iii) microglia/macrophage (M/Mφ) activation; (iv) natural killer (NK) cell infiltration and activation; and (v) cerebral levels of IL-15 and BDNF." (PMID 25818172, 2015). "Neuronal factors like neuroligin‐3 (NLGN3), brain‐derived neurotrophic factor (BDNF), and insulin‐like growth factor‐1 (IGF‐1) stimulate glioma proliferation." (PMID 40685688, 2025). "For example, brain-derived neurotrophic factor (BDNF) is secreted in an activity-dependent manner and has been shown to enhance glioma cell survival, motility, and angiogenic potential through TrkB–ERK–VEGF signaling pathways." (PMID 40999491, 2025). "BDNF and glucose‐regulated protein 78 (GRP78) also contribute to this pro‐tumorigenic environment in gliomas, while IGF‐1 drives the growth of olfactory bulb glioma." (PMID 40685688, 2025). "Our findings identify hsa-miR-134-5p as a key molecule impeding glioma cell growth by curtailing the BDNF/ERK pathway, with the reversal by BDNF upregulation pointing to the potential of therapeutically exploiting the hsa-miR-134-5p/BDNF axis in glioma care." (PMID 38579169, 2024). "Alterations in genes in glioma cell cultures of II, III and IV Grades upon exposure to GQIcombi (bi-(AID-1-T) + SB431542, LDN-193189, purmorphamine, and BDNF)." (PMID 38988707, 2024). "Alterations in proteins in glioma cell cultures of II, III and IV Grades upon exposure to GQIcombi (bi-(AID-1-T) + SB431542, LDN-193189, purmorphamine, and BDNF)." (PMID 38988707, 2024). "This study revealed that the C6 glioma cells induced by the Ani-AKH increased migrasome formation and expression of BDNF, and thus also increases the relationship between BDNF and migration." (PMID 38775506, 2024). "Brain‐derived neurotrophic factor (BDNF) provides another example; it orchestrates the trafficking of AMPAR to the postsynaptic membrane of glioma cells, a process intricately regulated by neuronal activity." (PMID 38567664, 2024). "Recent studies have shown that nerve growth factor (NGF), neurotrophins (NTs), synaptic adhesion molecule neuroligin, and brain-derived neurotrophic factor (BDNF) promote the initiation, progression, and invasion of gliomas." (PMID 37788099, 2023). "Together, these data illustrate that BDNF increases the strength of glutamate-evoked currents, including at AMPAR-mediated neuron-to-glioma synapses." (PMID 37914930, 2023). "Confirming that glioma cell TrkB activation mediates the change in glutamate-evoked current amplitude, NTRK2 knockout prevented the BDNF-induced increase in glutamate-evoked inward current amplitude, compared with NTRK2 wild-type glioma xenografted cells." (PMID 37914930, 2023). "NTRK2 signalling, mediated by the soluble brain-derived neurotrophic factor BDNF, plays a major role in cell survival promotion of growth in glial tumours." (PMID 35473984, 2022). "Such a new complex can increase the expression of different genes involved in neuronal differentiation, such as BDNF, NGF, or NFT3, maintaining the pluripotency of malignant cells and thus increasing the aggressiveness of the glioma." (PMID 35054945, 2022). "Subsequent investigations revealed that the induction of neuronal hyperactivity resulted in the release of secreted factors by neurons, such as BDNF or NLGN3, which support glioma progression and facilitate the synapsing of neurons onto glioma cells." (PMID 33187183, 2020). "CM from depolarized neurons contained a large amount of BDNF, neuroligin‐3, CA11 and CA10, and CM promoted cell proliferation in two glioma cell lines." (PMID 30636076, 2019).
glioma (continued). "BDNF/TrkB and NT3/TrkC signaling complexes have been shown to promote CSCs survival via AKT and Extracellular signal–Regulated Kinases (ERK) pathways in glioma." (PMID 31812953, 2019). "In high-grade gliomas, Xiong and collaborators demonstrated that the BDNF promoted cell migration and invasion through TrkB and p75NTR, whereas proBDNF had the opposite effects." (PMID 30190671, 2018). "TFSA, with the similar chemical structure, can also promote the proliferation of C6 glioma cells, and its mechanism has been related to TrkB/BDNF/ERK and TrkB/BDNF/PI3-K signaling pathways." (PMID 27729863, 2016). "BDNF infusion reduces M/Mφ infiltration and CD68 immunoreactivity in tumour mass and reduces glioma migration inhibiting the small G protein RhoA through the truncated TrkB.T1 receptor." (PMID 25818172, 2015). "We observed robust activation of the expression of BDNF exon I and IV as well as novel exon V, VIII, and IXA transcripts in rat C6 glioma cells after 5AzadC treatment." (PMID 17149751, 2007). "Its effects are not unilaterally protumorigenic: mature BDNF/TrkB signaling drives glioma growth, migration, and anti-apoptotic effects, while proBDNF/p75NTR activation inhibits these processes." (PMID 41018101, 2025). "The immunofluorescence positive staining for BDNF was detected throughout the cytoplasm from the perinuclear region of rat C6 glioma cells (data not shown)." (PMID 38775506, 2024). "Notably, both brain‐derived neurotrophic factor (BDNF) and synaptic protein NLGN3 are instrumental in the proliferation of glioma through paracrine secretion in the TME." (PMID 39469896, 2024). "In conclusion, the upregulation of hsa-miR-134-5p exerts inhibitory effects on the proliferation, migration, and invasion of U251 and U87 cells through modulation of the BDNF/ERK1/2 signaling pathway, thereby playing a crucial role in suppressing glioma occurrence and progression." (PMID 38579169, 2024). "Moreover, they compared the effects of NLGN3 and BDNF on glioma, reporting that while NLGN3 upregulates the expression of AMPAR subunits, BDNF-TrKB signaling promotes AMPAR subunit trafficking to the glioma cell membrane." (PMID 38473812, 2024). "In low-grade gliomas compared to non-neoplastic brain tissue, the ratio of pro-BDNF to mature-BDNF was reduced by 17%, while for GBM, the reduction was 44%, explaining GBM aggressiveness and its invasive nature." (PMID 37686652, 2023). "Given the findings above that BDNF increased AMPAR-mediated currents and calcium transients in glioma, we next investigated the effect of BDNF on AMPAR trafficking to the cell membrane in glioma cells." (PMID 37914930, 2023). "The effects of cortical projection neuronal activity on glioma proliferation were markedly attenuated in Bdnf-TMKI mice lacking activity-regulated BDNF expression and secretion." (PMID 37914930, 2023). "The fractions were lyophilized and then screened for modulation of neurotrophic (BDNF: brain-derived neurotrophic factor; and GDNF: glial cell-derived neurotrophic factor) and neuroprotective (HSP70: heat shock protein 70) signaling in C6 glioma cells at an initial concentration of 50 μg/mL." (PMID 34299002, 2021). "Furthermore, the increase in glutamate release stimulates peritumoral neurons to release BDNF and Neuroligin 3 (NLGN3) that in turn stimulate the glioma cells to proliferation and infiltration and sustained NGS formation." (PMID 34489641, 2021). "Previously, we demonstrated that in the absence of p75NTR, glioma cells secrete high levels of brain-derived neurotrophic factor (BDNF) protein into the culture medium in vitro." (PMID 19067488, 2008). "Additionally, a recent trial found exercise with augmented reality during radiotherapy mitigated strength/cognition declines in high‐grade gliomas, despite no BDNF impact." (PMID 40792048, 2025).